PGC (progastricsin)
Diseases named in the same sentence as PGC in open-access papers (continued):
Sharing a sentence is not in itself a finding about the gene and the disease.
dysplasia (1 paper, 2025). A usually neoplastic transformation of the cell, associated with altered architectural tissue patterns. "Exceptionally, IGHV3-43, IGHV4-31, IGHV3-53, and PGC top-ranked genes were validated in FFPE samples from patients diagnosed with BE with and without dysplasia due to their lack of expression in the cell lines." (PMID 40620772, 2025).
endometrial carcinoma (1 paper, 2020). A malignant tumor arising from the epithelium that lines the cavity of the uterine body. "It is worth noticed that all PGC, PGA3, and PGA5 genes had a certain degree of mutation in endometrial carcinoma, which is a tumor with high global mutation rate." (PMID 33067881, 2020).
Hypertension (1 paper, 2017). The presence of chronic increased pressure in the systemic arterial system. "However, we are unable to state this for the PGC gene, because we could not find clear evidence for an effect on blood pressure with hypertension and weight gain." (PMID 28924246, 2017).
medulloblastoma (1 paper, 2025). A malignant, invasive embryonal neoplasm arising from the cerebellum. "We did, however, observe a tendency towards a more abundant use of especially pGC in patients with medulloblastoma compared with patients with pilocytic astrocytoma." (PMID 40643729, 2025).
mucinous adenocarcinoma (1 paper, 2013). An invasive adenocarcinoma composed of malignant glandular cells which contain intracytoplasmic mucin. "When analyzing different histological GC groups, we found the phenotype of PGC-/MUC1-/MUC2+ all distributed in the group of mucinous adenocarcinoma or signet ring cell carcinoma (MA or SRCC, 100%, 6/6)." (PMID 23937908, 2013).
retinal detachment (1 paper, 2008). An eye emergency condition which may lead to blindness if left untreated. "After retinal detachment, the activity of both sGC and pGC could be reduced, since certain populations of retinal cells, such as the photoreceptor or Mϋller cells, may have undergone degenerative changes induced by hypoxic or ischemic alterations following the detachment." (PMID 18334939, 2008).
schizophrenia (1 paper, 2017). A major psychotic disorder characterized by abnormalities in the perception or expression of reality. "In support of this possibility, our recent MRI/genetic/epigenetic preliminary data showed that variation in methylation of PGC gene loci is more robustly related to GM concentration reductions in schizophrenia than the variability in the risk-conferring SNPs themselves." (PMID 28659829, 2017).
Sepsis (1 paper, 2014). Sepsis is defined as life-threatening organ dysfunction caused by a dysregulated host response to infection. "Although PGC-1a induction has not been previously shown to be linked to mtDNA repair, it is possible that PGC-1ainduction may lead to increase in OGG1, resulting in increased mtDNA repair, and renal protection against oxidative stress in sepsis." (PMID 24988481, 2014).
tubular adenocarcinoma (1 paper, 2013). An infiltrating adenocarcinoma in which the malignant cells form tubular structures. "The phenotype of PGC-/MUC1-/MUC2+ may be a predictive biomarker for diagnosing MA or SRCC or distinguishing from tubular adenocarcinoma accompanied by mucinous secretion or signet ring cell scattered distribution." (PMID 23937908, 2013). "The phenotype of PGC-/MUC1-/MUC2+ may be a predictive biomarker for diagnosing MA or SRCC, or distinguishing histological MA or SRCC from tubular adenocarcinoma accompanied by mucinous secretion or signet ring cell scattered distribution." (PMID 23937908, 2013).
viral infection (1 paper, 2022). "These four molecules are characteristic of each subtype, including: SEZ6 for autoimmune subtype, SPOCK3 for inflammation, FSD1 for viral infection, and PGC for oxidative stress." (PMID 36713418, 2022).
cancer (25 papers, 2008 to 2024). A tumor composed of atypical neoplastic, often pleomorphic cells that invade other tissues. "High PGC expression was linked to poor OS in several cancer types, including KIRC (log-rank p-value = 0.029) and MESO (log-rank p-value = 0.029)." (PMID 39767224, 2024). "Currently, the study of PGC’ role in cancer is mainly focused on only the relationship between PGC expression and incidence risk, clinical pathological parameters and prognosis." (PMID 28546787, 2017). "A PUBMED ID is provided if the PGC is known to be associated with cancer." (PMID 35672401, 2022). "The PGC was also significantly enriched in components related to integrin signaling (p = 2.33E−04), a complex signaling pathway implicated in both positive and negative regulation of tumor cell growth and cancer metastasis." (PMID 18636107, 2008). "Our results thus suggest the existence of a generalized homeostatic mechanism in solid tumors for maintaining precise levels of PGC transcription, which may be important for various cancer-associated phenotypes, such as tissue invasion and metastasis." (PMID 18636107, 2008). "A comprehensive and in-depth exploration and evaluation of the effects of PGC on cancer cells’ biological functions and the underlying molecular mechanisms will help to explain the role of PGC in the occurrence and development of cancer." (PMID 38791874, 2024). "The prognostic value of some pepsinogen family members, particularly PGC, has been established for other cancers." (PMID 39767224, 2024). "To examine the expression of PGC in a pan-cancer context, we analyzed its expression levels in various tumors and corresponding normal tissues using the TIMER database." (PMID 39767224, 2024). "Survival analysis was performed using the GEPIA tool to evaluate the prognostic value of PGC expression across various cancers." (PMID 39767224, 2024). "Conversely, some cancer types showed poor overall survival in the low PGC expression group compared to the high expression group." (PMID 39767224, 2024). "A similar phenomenon was observed with genes such as KRT4, LIPF, TG, and PGC, which are also almost exclusively expressed in specific tissues, making them less suitable for pan-cancer classification." (PMID 39118043, 2024). "PGs expression was significantly related to the activation or inhibition of many signal transduction pathways, in which PGC and PGA5 are more likely to be associated with cancer‐related pathways." (PMID 33067881, 2020). "As a cancer-related marker, monitoring the dynamic changes of PGC expression and cancer occurrence and development is of paramount significance." (PMID 28546787, 2017). "We functionally confirmed this association in siRNA knockdown experiments of five PGC genes (p53CSV, MAP3K11, MTCH2, CPSF6, and SKIP), which either directly enhanced the invasive capacities or inhibited the proliferation of AGS cancer cells." (PMID 18636107, 2008). "Third, the PGC genes also showed reduced expression variation in the NCI60 test set - a mixture of cancer cell lines from 9 different tissue types." (PMID 18636107, 2008). "Therefore, we aim to thoroughly investigate the expression profile of PGC with a pan-cancer approach, specifically in ESCA, and understand its significance in the progression of BE to EAC." (PMID 39767224, 2024). "Our study includes a pan-cancer expression analysis of PGC across all TCGA cancers, revealing its broad-spectrum presence and suggesting that PGC could serve as a diverse biomarker/target in human cancers." (PMID 39767224, 2024). "Interestingly, PGC expression varies across cancers and is frequently upregulated in certain sex-related cancers, such as prostate, breast, and ovarian cancers, where higher levels are associated with improved prognosis." (PMID 39767224, 2024). "Cluster 0 cells show overexpression of PGC that could be correlated with the regulating metabolic reprogramming in cancer cells." (PMID 37736108, 2023).
cancer (continued). "Therefore, we further analyzed and visualized the relationship between PGC and cancer‐related pathways in order to further clarify the molecular significance of PGC gene in pan‐tumorigenesis." (PMID 33067881, 2020). "Furthermore, we drew a forest map in which PGC showed different prognostic correlations in different types of cancers." (PMID 33067881, 2020). "The PGC genes exhibited minimal expression variation across the lines when assessed using a standard range of expression variation, consistent with their being tightly regulated in cancers (left heat-map)." (PMID 18636107, 2008). "We then asked if the precision of PGC regulation in cancer could be observed in independent data sets of diverse tumors." (PMID 18636107, 2008). "The latest bioinformatics analysis found that PGC may play a little-known role in the carcinogenic process, but there is no relevant experimental evidence to prove the effect of PGC on the biological function of cancer cells." (PMID 38791874, 2024). "The PGC gene cassette reported here may indicate such fragilities in the network of tumor cells, as subtle alterations on these components significantly affected the cellular behavior of cancer cells." (PMID 18636107, 2008). "Using the count data of 33 human tumors covered by TCGA, we analyzed the differential expression of PG family genes including PGC, PGA3, PGA4, and PGA5 in different cancers at the overall level based on continuous variable analysis." (PMID 33067881, 2020). "Compared with other multi-cancer biomarkers, our multi-NCA signature was more accurate in the per tissue analysis than the CIN, CIN70, PGC, LYM, and MES signatures." (PMID 26202601, 2015). "When PanIN samples were compared to PDACs, the most commonly up-regulated genes in the cancers were POSTN, COL1A2, SULF1, FN1, IGHM, VCAN and XIST, and these down-regulated were PGC and PPY." (PMID 23372777, 2013). "Although these cancer types showed a trend of decreased survival probability in low PGC expression patients, statistical significance was not achieved." (PMID 39767224, 2024). "Proteases present in malignant tumours but not in normal skin included: PGC, BAP1, caspase-8, F13A1, MMP11, MMP23, MMP25, MMP26 and granzyme-A." (PMID 35327667, 2022). "Our findings suggest that PGC and PGA5 had different effects on the prognosis of many kinds of cancers and they may be used as predictors of the prognosis in different cancers." (PMID 33067881, 2020). "In the cancer region we for instance observe enrichment of SPINK1 and PGC, and depletion of ACPP." (PMID 29925878, 2018). "Pepsinogen C (PGC) decreases gradually during progression of cancer, which makes PGC an ideal negative marker for GC." (PMID 29963765, 2018). "Although the role of PGC in HCC is still unknown, the common pathway of tumour growth or tumorigenesis between HCC and other PGC-producing cancers may be found." (PMID 28546787, 2017). "In stark contrast to the cancer data sets, the PGC genes exhibited either no or only a marginal degree of tight regulation in the normal data sets (p = 0.07 and 0.01)." (PMID 18636107, 2008). "Taken collectively, these results suggest that the identification of the PGC, and its restricted expression variation in cancers, is unlikely to be due to a technical artifact or the inclusion of a specific cancer type." (PMID 18636107, 2008). "Thus, an array of biological and functional evidences suggest that the PGC genes are likely to be involved in the activity of multiple cancer-related pathways, and not ubiquitous ‘housekeeping’ cellular functions." (PMID 18636107, 2008). "It is also important to note that the PGC genes do not exhibit significant differences in their absolute mean expression levels between cancers and normal tissues, but instead only differ in their levels of expression variation between cancers and normal tissues." (PMID 18636107, 2008).
cancer (continued). "Thus, the reduced expression variation of the PGC in cancers is unlikely to be due to the PGC genes simply being either highly expressed, rendering the PGC distinct from some studies suggesting an inverse correlation between expression variation and absolute expression levels." (PMID 18636107, 2008).
tumor (22 papers, 1993 to 2025). "Concordant positive staining of at least one of MUC5AC or PGC was observed between all tumour‐organoid pairs." (PMID 41225774, 2025). "MTT, TUNEL, and flow cytometry were used to evaluate the anti-tumor effect of the pGC-siRNA on Siha cells." (PMID 34635698, 2021). "They found 26.3% positive PGC staining in GC, and the proportion of PGC-positive GC cells in well-differentiated tumours (50%) was significantly higher than that in moderately differentiated tumours (19.5%) and poorly differentiated tumours (21.9%)." (PMID 28546787, 2017). "Using a similar strategy to the RSS test sets, a significant fraction of the PGC genes were tightly regulated in all nine primary tumor data sets (p-value range: 0–0.002), confirming the existence of the PGC in a wide variety of solid tumors." (PMID 18636107, 2008). "Moreover, our findings propose an interesting potential tumor-suppressive/control role for PGC in ESCA, possibly due to its involvement in complex pathways." (PMID 39767224, 2024). "Therefore, our evidence suggests that PGC plays a role as a tumor suppressor gene in the process of GC development, invasion, and metastasis." (PMID 38791874, 2024). "PGC may act as a tumor suppressor gene in the development, invasion, and metastasis of GC." (PMID 38791874, 2024). "Among them, we selected five decreased (CCDC28B, SREK1IP1/P18SRP/SFRS12IP1, RASL10B, PHF21A/BHC80 and PGC) and two increased genes (IL-11 and CXCL2), by microarray, as differentiation-, splicing-, inflammation-, or tumor-related genes." (PMID 26701885, 2016). "Among the upregulated genes, PGC, AFP, AKR1B10 and GPC3 showed more than 30-fold increased expression in the HCC tumor group." (PMID 25217841, 2014). "Specifically, we found that the PGC gene set and other OXPHOS gene sets were highly negatively correlated with FLCN expression across these tumor types." (PMID 21162720, 2010). "The four most upregulated genes were pepsinogen C (PGC), alpha fetoprotein (AFP), aldoketo reductase family 1 member B10 (AKR1B10) and glypican 3 (GPC3), which showed greater than 30-fold higher expression in HCC tumors than adjacent non-tumor tissues." (PMID 25217841, 2014). "Ectopic PGC expression is present mainly in sex hormone-related tumours, and we speculate that the absence of PGC expression in GC and sex hormones may have co-effects on GC development or hormone receptor pathways." (PMID 28546787, 2017). "Two PGC genes - p53CSV and KIAA0247 have been reported to be induced in response to oxidative stress, and may influence this balance and the response of tumor cells to apoptotic stimuli." (PMID 18636107, 2008).
adenocarcinoma (3 papers, 2004 to 2023). A common cancer characterized by the presence of malignant glandular cells. "Immunohistochemically, PGC expression is significantly higher in well-differentiated than in moderately and poorly- differentiated adenocarcinoma of the pancreas, breast, and stomach." (PMID 37291517, 2023).
infection (3 papers, 2017 to 2022). The state of being infected such as from the introduction of a foreign agent such as serum, vaccine, antigenic substance or organism. "Therefore, serum PGC detection is suitable for determining the eradication efficacy of H. pylori, and the PGA/PGC ratio can act as an assessment criterion of eradication efficacy in the early stage of infection." (PMID 28546787, 2017).
prostate (1 paper, 2022). "Similarly to SMARCD1, we found that numerous downstream targets of SMARCD2 (e.g., PTGR1, TRMP8, PGC) and SMARCD3 (e.g., EGF, PIK3AP1, HSD3B1) were AR-driven genes that are involved in prostate tumorigenesis, progression and metastasis." (PMID 36611918, 2022).
PGC also shares sentences with these, for which no sentence is quoted: prostate carcinoma (3 papers); cholangiocarcinoma (2); colon adenocarcinoma (2); lung adenocarcinoma (2); lung squamous cell carcinoma (2); prostate adenocarcinoma (2); rectum adenocarcinoma (2); uterine corpus endometrial carcinoma (2); atopic dermatitis (1); autoimmune gastritis (1); Azoospermia (1); Barrett esophagus (1); basal cell carcinoma (1); bladder cancer (1); bladder urothelial carcinoma (1); cardiac hypertrophy (1); cardiomyopathy (1); choriocarcinoma (1); colorectal cancer (1); dependence (1); depression (1); ductal carcinoma (1); eczema (1); gastric adenoma (1); gastric ulcer (1); gastroesophageal reflux (1); Helicobacter pylori (1); infectious disease (1); invasive lobular carcinoma (1); leukemia (1).
A further 14 diseases each share a sentence with PGC in 1 paper.